BRAF (B-Raf proto-oncogene, serine/threonine kinase)
Diseases named in the same sentence as BRAF in open-access papers (continued):
Sharing a sentence is not in itself a finding about the gene and the disease.
cancer (continued). "BRAFV600E is the most frequent mutation in BRAF (serine/threonine-protein kinase B-raf), a proto-oncogene and the most commonly mutated kinase in human cancers." (PMID 36698391, 2022). "The results showed that BRAF expression, alteration frequency, mutation site distribution, and DNA methylation patterns varied tremendously among different cancer types." (PMID 35910024, 2022). "Remarkably, YAP activation has been reported to be associated with stemness, conversion of normal fibroblasts to cancer-associated fibroblasts (CAFs), and resistance to BRAF and/or MEK inhibitors." (PMID 35440004, 2022). "The 848 BRAF somatic mutations were observed in various cancer types and widely distributed across different functional domains of the BRAF gene." (PMID 35910024, 2022). "Taken together, our data indicate that cancer-derived BRAF mutations occurring in the SBC motif allow BRAF to evade SPOP-mediated ubiquitination." (PMID 36585710, 2022). "In contrast to the mutual exclusivity of mutations in oncogenes KRAS and BRAF, cancers with PIK3CA mutations have often concomitant mutations in either of these genes of the KRAS/BRAF/MEK/ERK pathway." (PMID 36295658, 2022). "We studied ctDNA and tissue biopsy to investigate EGFR, KRAS, NRAS, and BRAF mutations from 199 cancer patients between January 2016 and March 2021." (PMID 36497340, 2022). "Based on the molecular mechanism, a classification of BRAF mutations identified in cancer samples has been proposed: class 1 mutations mimic the phosphorylation of the activation loop and thereby lead to aberrant activation of the kinase domain." (PMID 36275468, 2022). "B-Raf proto-oncogene serine/threonine-protein kinase (BRAF) is frequently altered in multiple cancer types, and BRAF V600 mutations act as a prime target for precision therapy." (PMID 35910024, 2022). "In the future, the activity of chemoimmunotherapy and combinations of TKIs with chemotherapy, anti VEGF/VEGFR agents, and/or immunotherapy in patients with BRAF-mutated cancers needs to be determined." (PMID 35433454, 2022). "As a highly heterogenous cancer, CM harbours various genetic alteration including BRAF mutation, RAS mutation, NF1 mutations, etc., which plays an critical role in the biological behavior of CM and is closely related to the prognosis of CM patient." (PMID 35751033, 2022). "As such, the presence of the BRAF V600E mutation was significantly associated with increased cancer-related mortality, and this risk increased with age." (PMID 36329478, 2022). "Specific mutations in the RAS–RAF–MEK–ERK pathway are associated with 46% of all human cancers, with KRAS mutations in 9% and BRAF mutations in 7% of all human cancers." (PMID 35899070, 2022). "Since the identification of BRAF mutations among different types of cancers and the understanding of their pathological and clinical implications, several BRAF inhibitors (BRAFi) have been developed." (PMID 36230797, 2022). "When evaluated for mutation, 77.7% of cancers had BRAF V600E; 8.8% showed RET/PTC rearrangements; 4.4% were positive for PAX8/PPAr gamma and 9.1% had RAS mutations (H- and K-, no NRAS mutations were found in our series)." (PMID 34350538, 2022). "SFG showed significantly higher mutation rates in BRAF-mutated than in BRAF-wildtype tumors in pan-cancer and in four individual cancer types (BRCA, COAD, STAD, and UCEC)." (PMID 36684432, 2022). "The Memorial Sloan Kettering-Integrated Mutation Profiling of Actionable Cancer Targets (MSK-IMPACT) study revealed that treatment with ICIs resulted in a similar OS in 27 BRAF mutated and 323 WT NSCLC patients with a median OS 10 m vs. 11 m, P = 0.334." (PMID 36543792, 2022). "Although BRAF mutation is an oncogenic driver in multiple cancers, a single-agent BRAF inhibitor has limited clinical efficacy in BRAF V600E-mutated COADREAD patients." (PMID 35910024, 2022).
cancer (continued). "Currently, the only such indicator is the presence of the V600E mutation in the BRAF gene in cancer cells, which qualifies the patient for therapy with inhibitors of the MAPK pathway." (PMID 35565444, 2022). "Of note, patients with BRAF mutations/MSI have good prognoses, followed by BRAF wildtype/MSS cancers, whereas patients with BRAF-mutated/MSS have the worst prognoses." (PMID 36077604, 2022). "In preoperative molecular FNAC diagnostics, the aggressiveness of cancers with the most frequently occurring mutations (BRAF, RAS, RET/PTC, TERT, PAX8/PPAR-γ, RET proto-oncogene) is correlated with the extent of the planned surgical treatment." (PMID 35884820, 2022). "Up to this day, mutations in BRAF have been reported extensively in a variety of benign and malignant tumors." (PMID 35344507, 2022). "Somatic mutations in cancer-driving oncogenes such as BRAF, PIK3CA, HRAS, and FGFR3 can be found in normal skin from elderly people, while younger people’s skins almost completely lack mutations in those genes." (PMID 36143375, 2022). "In contrast, expression of P2RY2A, a purinergic receptor subtype involved in the mobilization of cytosolic Ca2+ and implicated in numerous cancer hallmarks was downregulated only in BRAF muted cancer cells." (PMID 35267511, 2022). "This was in line with a previous report that the BRAF K601E mutation is strongly associated with follicular‐patterned cancer, particularly with the encapsulated follicular variant of PTC." (PMID 35247035, 2022). "Activating BRAF mutations, in particular V600E, drive the formation of many types of cancer, whereas inactivating mutations or WT BRAF cooperate with RAS via paradoxical ERK activation and cause resistance to the BRAF-selective inhibitors." (PMID 35585049, 2022). "In 2011, following the results of a phase III trial (BRIM-3), the FDA approved the first drug targeting BRAF-mutated cancers, PLX4032 (vemurafenib)." (PMID 35912223, 2022). "A 2012 meta-analysis associated BRAF mutation with more malignant cancers (i.e., advanced cancer diagnosis, LNM and extrathyroidal extension), accompanied by a two-fold increased risk of recurrence or persistent disease." (PMID 36009596, 2022). "ASN007 is a potent selective ERK1/2 inhibitor with promising antitumor activity in cancers with BRAF and RAS mutations." (PMID 34973117, 2022). "The BRAF V600E mutation was the most frequently occurring mutation which was detected in 3,905 cancer samples." (PMID 36275468, 2022). "Given that BRAF activity is elevated in SPOP-mutated cancers, the efficacy of AZ304 in these cancers should be investigated." (PMID 36585710, 2022). "First-generation RAF inhibitors (such as vemurafenib, dabrafenib, encorafenib), selective for the BRAF V600E mutant, showed efficacy in BRAF V600E mutated cancers." (PMID 35158933, 2022). "The most common activating BRAF mutation found in cancer is a point mutation in exon 15 (c.1799T > A) that corresponds to a valine to glutamate substitution at codon 600 (V600E)." (PMID 35454926, 2022). "PIK3CA mutations are frequently associated with other gene mutations which are involved in significant cancer-related pathways, such as the Wnt/beta-catenin pathway and tyrosine kinase receptors K-Ras/BRAF/MAPK." (PMID 35723313, 2022). "This suggests that MSS cancers are enriched in the metastatic setting and that MSI-associated BRAF mutated cancers progress less often to a metastatic stage." (PMID 36079062, 2022). "In the present study, BRAF mutation c.1799 T > A (p.V600E) was only observed in a single carcinoma sample that also displayed MSI-H status." (PMID 35173208, 2022). "V600E mutation in BRAF overexpressed carcinoma consist of near about 80% and other 20% remain in V600 K." (PMID 36267655, 2022). "The main genetic drivers of these chronic sun-damaged cancers are B-raf proto-oncogene (BRAF), neurofibromin-1 (NF-1), and NRAS mutations." (PMID 34155457, 2021).
cancer (continued). "Testing for single mutations such as BRAF V600E has a high specificity for cancer but low sensitivity." (PMID 32638211, 2021). "BRAF is one high frequency mutated kinase in human cancer and V600 a canonical mutation site in conserved domain, suggesting a significant ultilizing on clinical treatment and prognosis prediction." (PMID 34247571, 2021). "Targeting hyperactive RAS/RAF/MEK/ERK signaling with RAF inhibitors has achieved promising outcomes for treating cancers harboring BRAF(V600E) mutation." (PMID 35582307, 2021). "Of the 739 cell lines used in our pan-cancer analyses, 96 contain a missense (presumed activating) mutation in BRAF." (PMID 33328249, 2021). "Among the cancer driver genes analyzed, BRAF V600E was the most represented somatic mutation throughout the cohort." (PMID 33672345, 2021). "In a basket trial of patients with V600E mutated cancers, BRAF inhibitor (dabrafenib) and MEK inhibitor (trametinib) combination demonstrated a clinical response in 51% of patients." (PMID 34439216, 2021). "Our results demonstrated that canine TCC cells showed different responses compared to human cancer with the BRAF V600E mutation." (PMID 34502061, 2021). "Prete and others demonstrated that in cancer cells with BRAF mutations, therapeutic escape from BRAFi/MEKi was facilitated by pericytes that secreted thrombospondin-1 (TSP-1) and TGF-β1, both of which led to a rebound of pERK1/2, pAKT and pSMAD3." (PMID 34917620, 2021). "In this work, AuNPs and cetuximab-AuNPs with different sizes were synthesized and it was desired to study their cytotoxicity on BRAF-mutant HT-29 CRC cells (RAS wild-type) to advance the understanding of treatment response for cancers with BRAF mutation." (PMID 33499047, 2021). "The BRAF-V600E mutation can affect the molecular characteristics both in the primary cancers and metastases." (PMID 34319022, 2021). "A single point mutation (V600E) in the activation loop of BRAF represents > 90% of all cancer-related RAF mutations." (PMID 35582307, 2021). "Hundreds of BRAF mutations have been identified in patients with cancer but currently approved drugs only target BRAF V600 mutants." (PMID 33568647, 2021). "Currently, the first-generation RAF inhibitors have been approved for treating late-stage cancers with BRAF(V600E) mutations." (PMID 35582307, 2021). "Primary outcome measurement is enrichment of RAS (KRAS, NRAS and HRAS) alterations in BRAF variant cancers." (PMID 33507258, 2021). "Next, we tested the PHASIFY method in 91 clinical plasma samples from 34 unique patients collected at different time points with diverse advanced cancers and BRAF, KRAS or NRAS mutations." (PMID 34608196, 2021). "In A375 cells, knock-down of the BRAF gene caused a concomitant decrease in both pERK and cell proliferation, which was consistent with previous reports showing that cancer cells harboring BRAF V600E are addicted to ERK pathway." (PMID 33793658, 2021). "Here, we further our exploration of the utility of seriniquinone (SQ1) and its analogues (SQ2–SQ5) as agents that target cancer’s bearing point mutations on BRAF and NRAS genes." (PMID 34885944, 2021). "Following BRAF V600E‐mutation analysis, an additional four tumors were classified as cancer as they were mutation positive." (PMID 34156770, 2021). "Mutant BRAF was present in nine of 146 of cancer cell lines, and this oncogenic mutation was found to be associated with dependency on 50 genes in these cancer types." (PMID 32767816, 2021). "RePhine predicted that loss-of-function of EZH2/PRC2 reduces cancer cell sensitivity toward the BRAF inhibitor PLX4720." (PMID 33713851, 2021).
cancer (continued). "The recommended phase II dose was 40 mg in patients with cancer harboring BRAF or KRAS/NRAS mutations." (PMID 33474634, 2021). "Driver mutations in BRAF are found in a variety of cancers and are characterized by activating hotspot mutations in the kinase domain of the gene, most notably the p.V600E mutation." (PMID 34211036, 2021). "Single mutation or concomitant mutations in both KRAS and BRAF genes have been identified in different type of cancers." (PMID 34578339, 2021). "The BRAF gene is frequently mutated in several cancers, and BRAFV600 is the most common mutation of the skin." (PMID 34571969, 2021). "The EGFR L858R and T790M, and BRAF V600E genetic variants are important mutation term features in text mining and are frequently mutated in cancer." (PMID 34759963, 2021). "There is emerging pre-clinical and clinical evidence that BRAF or upstream KRAS mutations in cancer cells results in heightened radiation resistance." (PMID 34537078, 2021). "Several seminal studies over the past decades have delineated upstream factors of MEK1 correlate with a greater risk of cancers, such as BRAF." (PMID 34526571, 2021). "In canine cancer, which shares similarities with human cancer, activating BRAF mutations play an important role in driver alteration by using the same signaling pathways." (PMID 34502061, 2021). "In another study, the combined effects of APC and BRAF mutation were tested in mice to determine the mutational landscape of WNT signaling regulators in BRAF mutant cancers." (PMID 34488905, 2021). "Mutations in PIK3CA are associated with higher rates of mutations in other genes of important cancer-associated pathways such as the tyrosine kinase receptors/K-Ras/BRAF/MAPK and the Wnt/β catenin pathway." (PMID 33435133, 2021). "RAS-dependent BRAF variant cancers with different mechanisms of RAS activation suggest the need for different treatment strategies." (PMID 33507258, 2021). "Inhibition of the RAF-MEK1/2-ERK signaling pathway is an ideal strategy for treating cancers with NRAS or BRAF mutations." (PMID 34064422, 2021). "BRAF mutation is an oncogenic driver, and the Cancer Genome Atlas has identified BRAF mutations in different cancer types." (PMID 33669326, 2021). "The expression of FASN was found to be inversely associated with drug resistance in BRAF-mutant cell lines, both in a set of six resistant/sensitive matched lines and in the Cancer Cell Line Encyclopedia." (PMID 34068792, 2021). "Here, we show that LT, through inhibiting MEK1/2-ERK activation, inhibits the proliferation of cancer cells with NRAS/BRAF mutations." (PMID 34064422, 2021). "Knockdown by RNAi or treatment with a BRAF-selective inhibitor leads to the inhibition of cell proliferation and survival in BRAF-mutated cancer cell lines." (PMID 33793658, 2021). "Fibroblasts in particular frequently make up a major part of the stroma, and their involvement in cancer initiation and progression has been well documented for several tumor types with high prevalence of BRAF mutations." (PMID 34930313, 2021). "Although it has been reported that BRAF mutations are more common in advanced stages, few studies have focused on early stage cancer." (PMID 34884530, 2021). "Many lines of evidence suggest that BRAF MT is associated with the upregulation of MMP9 expression in several cancers." (PMID 34069882, 2021). "Given the fact that clinical trials with BRAF inhibitors produced various outcomes in different carcinomas, we performed a pan-cancer analysis for BRAF mutations." (PMID 34630336, 2021). "The RAS-RAF-MEK-ERK pathway is altered in forty percent of all human cancers, mainly due to mutations in BRAF and its upstream activator RAS." (PMID 33802234, 2021). "For example, the unweighted studies found VHL and BRAF mutations incident at 7 and 2%, respectively, while our weighted study estimates these genes to be mutated in 1 and 8% of the cancer population." (PMID 34645806, 2021).
cancer (continued). "In BRAF/MEK inhibition-resistant cancer cells carrying BRAFV600E mutation, the dual MAPK inhibition drives the overexpression of FGF1 followed by the FGFR activation and the reactivation of ERK." (PMID 34830951, 2021). "Understanding RAS dependency and mechanisms of RAS activation in non-V600 BRAF variant cancers has important clinical implications." (PMID 33507258, 2021). "For example, in BRAF-mutated cancers, BRAF inhibition leads to endoplasmic reticulum (ER) stress, which subsequently increases autophagic activity, protecting the cells from apoptosis and maintaining mitochondrial activity." (PMID 34835393, 2021). "Genetic alterations that aberrantly activate this kinase pathway in cancers are typically the result of BRAF or KRAS mutations in the majority of cancers displaying MAPK activation." (PMID 34046359, 2021). "PETN~BRAF sequential mutations were significantly more common than AKT1~BRAF sequential mutations in hypermutated cancers." (PMID 34503126, 2021). "Although FDA-approved inhibitors of BRAFV600E/K have revolutionized the treatment of certain BRAF-mutated cancers, the twin phenomenon of primary or acquired chemoresistance remains a major clinical challenge." (PMID 34298710, 2021). "The RAS-regulated RAF–MEK1/2–ERK1/2 pathway promotes cell proliferation and survival and RAS and BRAF proteins are commonly mutated in cancer." (PMID 33367512, 2021). "Secondary outcome measurement is enrichment of RAS regulatory gene (NF1, PTPN11, and CBL) in BRAF variant cancers." (PMID 33507258, 2021). "Of the six represented cells lines, five had mutations in the BRAF gene: four with the typical BRAF V600E mutation and one with BRAF I326V, which has been found in other cancers (colorectal, breast, and lymphoid)." (PMID 34589115, 2021). "The selective action of high levels of vitamin C on cultured cancer cells harboring KRAS or BRAF mutations has been demonstrated for the first time in colon cancer, which commonly harbors these genetic mutations." (PMID 34065197, 2021). "BRAF V600E, a recurrent biomarker for approved drugs (level A) in multiple cancer types, shows diverging associations with young adult status." (PMID 34788626, 2021). "Mutational activation of BRAF is a driver of numerous cancer types, including both solid and hematologic malignancies." (PMID 34298710, 2021). "The predominant BRAF mutation (V600E) is found within the kinase domain and leads to the constitutive activation of downstream signaling in cancer cells." (PMID 34771574, 2021). "Hyperactivation of the MEK1/2-ERK signaling axis due to mutations in NRAS and BRAF drives oncogenesis in ~30% of human cancers, and targeting RAF and MEK can be a curative therapy for these cancers." (PMID 34064422, 2021). "Recent studies have revealed that the v-Raf murine sarcoma viral oncogene homolog B (BRAF) mutation rates are high in certain cancers and the most common is BRAF V600E, with variable mutation rates in different populations." (PMID 33451059, 2021). "These included the following genes known for their association with cancer: BRAF (V600E) and PIK3CA (E545K), both harboring hotspot mutations and three other possible driver genes, SDHC (H127R), DDR2 (R668C), and FANCD2 (C1130Y)." (PMID 34301805, 2021). "Around 2% of BRAF-mutant (BRAF-mt) cancers have non-V600E BRAF mutations, the prognostic and predictive value of which is still not clear." (PMID 34249672, 2021). "Activating point mutations or small in-frame deletions observed in BRAF-mutated cancers generally occur within sequences that encode the protein kinase domain." (PMID 34298710, 2021). "Of the three Raf isoforms, ARaf, BRaf, and CRaf, BRaf is the isoform more commonly mutated in cancer." (PMID 34680208, 2021).